ATRX (ATRX chromatin remodeler)
Diseases named in the same sentence as ATRX in open-access papers (continued):
Sharing a sentence is not in itself a finding about the gene and the disease.
tumor (continued). "In cancer, this is especially important for tumour suppressors, e.g., ATRX, DDX3X." (PMID 35661403, 2022). "Numerous prognostic genomic features have been characterized as predictors of survival for pNENs, including mutations in DAXX/ATRX and MEN1, the expression levels of somatostatin receptors 2 and 5, elements of the tumor immune microenvironment, and enzymes involved in hormone metabolism." (PMID 36969744, 2022). "Thus, loss of ATRX leads to increased genome instability manifested as elevated DSBs, increased CFS expression, and micronuclei formation, which can influence tumor progression and therapy response in cancer patients." (PMID 35406561, 2022). "In order to investigate whether the increased tumor size found with ATRX KO was due to differences in tumor cell proliferation or apoptosis, IHC was performed on the formalin-fixed, paraffin-embedded xenograft tumors harvested from these mice." (PMID 36073547, 2022). "ATRX knockdown significantly enhanced tumor growth in these xenografts for both shRNAs." (PMID 36073547, 2022). "We also identified some gene mutations (ATRX, and MUC16) in different stemness subtypes, which might be potential targets for STS to regulate stemness of tumor cells." (PMID 35464409, 2022). "Tumor cells showed retained nuclear expression of ATRX protein." (PMID 36611369, 2022). "The loss-of-function of ATRX and, less frequently, DAXX affects telomeric stability and results in telomerase-independent maintenance through alternative lengthening of telomeres (ALTs) in H3.3G34R/V mutant tumour cells." (PMID 35382567, 2022). "Our successful attenuation of xenograft tumor growth, as well as tumor cell migratory and invasive capabilities with the integrin inhibitor SB273005, supports the importance of integrin binding for increased OS aggression correlated with ATRX loss." (PMID 36073547, 2022). "Some studies imply ATRX mutations based on a single strict criterion; that is, no staining of any tumor nuclei." (PMID 34458259, 2021). "Deciphering the specific role of ATRX mutations to the tumour neurobiology has not been established to date, although there is some evidence to suggest it has a role in cell cycle regulation, histone regulation, and chromatin remodelling." (PMID 33477674, 2021). "The withdrawal A (from LMD), besides the absence of tumour invasion, displayed loss of ATRX expression in pTERT wild type tumour cells." (PMID 34573966, 2021). "Since ATRX loss of function and MYCN amplification are reported to be mutually exclusive, and 11q deletion is very rarely observed in MYCN-amplified tumours, we propose PARP and ATR inhibitors may be beneficial to a large subset of high-risk NB patients." (PMID 34944835, 2021).
tumor (continued). "Immunohistochemistry was used to detect the ATRX expression level of the tumor tissue." (PMID 34729095, 2021). "ALT tumours are frequently inactivated for ATRX, yet inherited mutations in ATRX (underlying the ATR-X syndrome) do not have appreciable effects on cancer predisposition." (PMID 33972520, 2021). "DAXX and ATRX are mutually exclusive inactivating mutations, and no tumor with a mutation in ATRX had a mutation in DAXX." (PMID 34026777, 2021). "In view of the young age of the patient, negative IDH1 R132H mutant protein and loss of ATRX expression in the tumor cells, IDH1/2 Sanger sequencing was performed to look for a noncanonical IDH mutation." (PMID 34647024, 2021). "In our cohort, the PDX1 gene presented hypermethylated CpG sites in the tumours in subgroups T2 and T3 (mutant ATRX/DAXX/MEN1) compared to tumours in the subgroup T1, which are mainly wild-type for those genes and this subgroup was enriched for functional tumours." (PMID 33536587, 2021). "Most intriguingly, RNA-Seq analysis showed that expressing WT DAXX in G292 also upregulated the pathway related to osteoblast differentiation, suggesting that re-expression of WT ATRX/DAXX in OS cells may stop tumor growth by inducing re-differentiation." (PMID 34069193, 2021). "Altered cases were not enriched in any annotation (i.e., histotype, tumor site, grade, metastasis, or sex), but had a significantly lower mRNA expression of ATRX (p = 0.0362) and were significantly associated with ALT (p = 0.00396)." (PMID 33946962, 2021). "Finally, two patients in this series presented M-LGG with divergent ATRX/1p19q status between the tumor foci, challenging the discouragement of the diagnosis of “oligoastrocytoma” in tumors with mixed histopathological aspects." (PMID 33673104, 2021). "Furthermore, we were able to stain serial tumor specimens with antibodies to DAXX and ATRX, the mutation status of which has been added to the criteria of well-differentiated NETs." (PMID 33108599, 2020). "For ATRX mutation prediction, the single most predictive feature was the average T1 postcontrast intensity within the tumor core followed by the MD kurtosis within the non-enhancing tumor." (PMID 32678261, 2020). "Among ERGs that could be classified as tumor suppressors, KMT2D, KMT2C, ARID1A, ATRX, CREBBP, and PBRM1 were frequently mutated in many cancer types, whereas oncogenic ERGs were each mutated in specific cancer types, mainly IDH1 in LGG and DNMT3A in LAML." (PMID 32963031, 2020). "After adjustment for WHO grade, MGMT, Ki67, and TERT, molecular group of IDH1 and ATRX were associated with tumor growth in univariable analysis but not in the multivariable model." (PMID 32388499, 2020). "Additionally, while PDX1 expression appears to be specific for benign and low stage tumours, ARX expression is retained at early and at advanced stages and only DAXX/ATRX status provides more information about stage and risk of disease progression." (PMID 33288854, 2020). "Somatic mutations in ATRX, DAXX, or TERT were found in 16% of tumor samples." (PMID 32024817, 2020). "This enrichment was confirmed in a subset of primary ATRX/DAXXtrunc tumor samples in our study." (PMID 32024817, 2020). "Further study is needed to resolve this controversy regarding the prognostic value of chromatin remodeling alterations including MEN1, DAXX, and ATRX, which may be tumor stage and grade-specific." (PMID 31692857, 2019).
tumor (continued). "IHC performed on SCR shRNA xenografts showed the tumour cells to be negative for the expression of the IDH1R132H‐mutated protein product with strong nuclear ATRX expression and GFAP and EGFR immunopositivity." (PMID 30565681, 2019). "To gain insight into the feasibility of using the mutant HSV-1 as a therapy for ATRX-deficient tumors, we confirmed that mutant HSV-1 replicates ∼1000-fold more effectively in ATRX-deficient tumor cells than in ATRX-expressing fibroblast or healthy epithelial cells." (PMID 30745338, 2019). "Consistent with the analysis in our tumor samples, SLX4IP deficiencies in our cell lines are mutually exclusive with ATRX, DAXX, SMARCAL1, and H3.3, raising the possibility that SLX4IP may represent another gene deficiency associated with ALT activity." (PMID 31447390, 2019). "MYCN amplification, activating mutations in the ALK receptor tyrosine kinase, TERT rearrangements, inactivating ATRX mutations and dominant negative mutations in PHOX2B are among the most recurrent genetic events that drive oncogenic signaling and tumor formation." (PMID 30952905, 2019). "Similar to a number of recent studies, we have demonstrated in this cohort of PanNETs that, in additional to pathologic stage and grade of the tumor, mutations in DAXX, ATRX, and MEN1 are associated with adverse clinical outcome in comparison to those without these mutations." (PMID 30315258, 2018). "Half of the patients (n = 30) had MGMT promoter methylation, and 13 patients showed ATRX mutation, while none of patients had 1p/19q co-deleted tumor." (PMID 30375429, 2018). "However, while IT and MLP tumours from human and mouse clustered together, MEN1-like tumours formed a compact subgroup that clustered far from the mouse model and were enriched in mutations of chromatin remodeling genes (MEN1, DAXX, ATRX)." (PMID 29321190, 2018). "ATRX or DAXX loss was proved to be an independent predictor for OS of PanNETs in a multivariate Cox regression analysis including well-established risk factors; tumor stage and tumor grade." (PMID 28591701, 2017). "ATRX expression was positive in tumor cells and reactive astrocytes." (PMID 29207673, 2017). "The association of ATRX and DAXX inactivation with the ALT phenotype might explain previous observations in other tumor types that connected the ALT phenotype with improved prognosis." (PMID 28591701, 2017). "ATRX and DAXX mutations with ALT activation have been reported to correlate significantly with tumor size and T-stage, and are thus considered a late event in tumor progression." (PMID 27267993, 2016). "In this report, we link the induction of ALT with the presence of a DNA secondary structure and this may also explain why ATRX is being increasingly identified as a tumour suppressor in a wide variety of ALT-positive tumours." (PMID 26143912, 2015). "Tumor grade was correlated with the mutational load (the number of non-silent mutations) of the tumor: grade II diffuse gliomas harbour fewer genetic changes than grade III or IV, even within defined molecular subtypes (e.g. ATRX mutated diffuse gliomas)." (PMID 26699864, 2015).
tumor (continued). "Finally, we correlate ATRX mutation with ALT, recapitulating a functional association with mitotic instability seen in other ATRX-mutant tumor types." (PMID 23104868, 2012). "Consistent with the results of DNA methylation analysis, ATRX immunohistochemistry was performed (mouse monoclonal, clone BSB-108, dilution 1:2000, Bio SB, Santa Barbara, CA, USA) and showed a near complete loss of ATRX nuclear expression in tumor cell nuclei compared to non-neoplastic cells." (PMID 41397922, 2025). "ATRX may be a potentially effective target for tumour therapy." (PMID 39479502, 2024). "ATRX staining in tumor samples from patients 2 and 3 failed to display an adequate internal control staining in the stromal cell nuclei, and the tumor sample from patient 1 showed subsets of tumor cell nuclei with ATRX loss and ATRX retention." (PMID 39351526, 2024). "Notably, ATRX is a tumor suppressor that functions as a “guardian” of genome stability, and inactivation of its function due to mutations may potentially explain the observed increase in mutational burden in MAS98.12PR." (PMID 39390250, 2024). "One additional tumor showed an ATRX mutation without loss of staining on IHC." (PMID 39233831, 2024). "Importantly, four genes (MET, ATRX, ATR, and BRCA2) associated with active clinical trials were mutated specifically in one region of the tumours investigated, suggesting that may have been missed if tumour heterogeneity had not been considered." (PMID 39766052, 2024). "While ATRX mutations themselves are not currently direct therapeutic targets, their presence is valuable for prognostication and can help refine treatment approaches, especially when considering the overall molecular profile of the tumor." (PMID 39767571, 2024). "We demonstrated that among ATRX-deficient cell models, the presence of the IDH1 mutation has negligible impact on proliferation; however, upon intracranial implantation, mutant IDH1 significantly increases tumor aggressiveness, as indicated through a shorter survival and greater tumor penetrance." (PMID 38272925, 2024). "Additionally, ATRX mutations, EGFR (epidermal growth factor receptor) alterations, CD70, CD147, CDKN2A deletions, exosomes, cfDNA (cell-free DNA), ctDNA (circulating tumor DNA), and CTCs (circulating tumor cells) stand out as significant markers." (PMID 38732975, 2024). "Furthermore, mutations in the IDH1 gene, as well as depletion of histone chaperone ASF1, have been implicated in the activation of the ALT phenotype, indicating that ALT activation in tumor cells is not solely dependent on ATRX/H3-3A mutations." (PMID 37370681, 2023).
tumor (continued). "However, this serves as a reminder that the current understanding of ATRX as a tumor suppressor in digestive cancers is incomplete, as ATRX may also act as a tumor promoter depending on the context." (PMID 36428674, 2022). "As we have described, the interactions between ETS binding, NF-κB activation, integrin αvβ3 expression, and osteopontin expression have been closely linked with more aggressive tumor biology in prior studies across cancer types, but the association with ATRX expression has not been noted previously." (PMID 36073547, 2022). "However, more recent, large-scale analyses of cell lines and tumor samples identified a substantial fraction of ALT-positive samples that do not harbor ATRX mutations." (PMID 36030273, 2022). "Tumours harbouring DAXX or ATRX mutations have a different CIMP profile to non-mutated tumours." (PMID 35626118, 2022). "ADC values can vary within a single DMG between enhancing and non-enhancing tumor areas, maybe more frequently in cases with ATRX loss." (PMID 35326549, 2022). "Therefore, tumor-free survival was significantly poorer upon ATRX knock-down (p = 0.0097)." (PMID 33946962, 2021). "Therefore, they hypothesised that the ATRX gene may escape X-inactivation in certain specific tumour types that may account for the observed sex-bias." (PMID 33950317, 2021). "ATRX gene mutations are associated with a lack of ATRX expression in tumor specimens." (PMID 34220707, 2021). "In this respect, it is important to note that our study was limited to diffuse gliomas with oligodendroglial or mixed oligoastrocytic morphology, because IDH-mutant astrocytic-appearing tumours with ATRX loss can be confidently diagnosed as astrocytic without the need for 1p/19q codeletion testing." (PMID 34165590, 2021). "Furthermore, tumor response against DNA-damaging agents that cause double-stranded DNA breaks (DSBs) in ATRX-KO mice is improved by impaired non-homologous end joining repair." (PMID 31752169, 2019). "The identification of mutations in ATRX/DAXX genes in sporadic NENs, as well as the high burden of mutations scattered throughout the multiple endocrine neoplasia type 1 (MEN-1) gene in both sporadic and inherited syndromes, provided new insights into the molecular biology of tumour development." (PMID 31443481, 2019). "In addition, ATRX may play a driver mutation role for sporadic PPGL and truncated ATRX could potentially play a synergistic role with SDHx in tumor initiation and might be a predisposition for a more aggressive disease." (PMID 30538672, 2018). "No loss of ATRX protein expression was observed in tumours which met the WHO 2016 criteria for OG." (PMID 28030632, 2016). "Multivariate Cox regression analysis identified age, Karnofsky Performance Status (KPS) score, tumor diameter, WHO grade, and postoperative radiotherapy and chemotherapy, as well as the expression of ATRX, IDH1, and Ki-67, as independent prognostic factors." (PMID 41008886, 2025).